CD34 (CD34 molecule)
Diseases named in the same sentence as CD34 in open-access papers (continued):
Sharing a sentence is not in itself a finding about the gene and the disease.
tumor (continued). "By 4 weeks, when measureable tumor growth was first detected, there were still detectable huCD31(+) vessels while mouse CD34(+) blood vessels were also already abundant in the interior of the xenografts." (PMID 23639003, 2013). "To identify VM in primary human GBM sections, we used PAS and antibodies against CD34 and nestin to stain the tumor blood vessels." (PMID 23536763, 2013). "Appearance of CD34-tagged capillary was irregular and its distribution was uneven, which concentrated mainly at the edge of tumor invasion." (PMID 23325045, 2013). "These 3 tumours presented as nodular, well-encapsulated masses with vascularised component are all diagnosed on morphology and immunohistochemical profile (CD34 positivity)." (PMID 22566753, 2012). "Significantly more tumor vessels stained positive for CD34 in the center of the tumor compared to the periphery." (PMID 23153292, 2012). "CD34+ tumor cells were shown to express higher levels of VEGF than CD34− tumor cells or normal keratinocytes." (PMID 23125933, 2012). "The antiangiogenic effect was proved by CD34 immunostaining with marked decrease of MVD in LLC tumor tissues treated with K5." (PMID 23300882, 2012). "The present study evaluated CD34 staining as marker of tumor vascularity in biopsies with NHL and comparison of various types of NHLs and reactive follicular hyperplasia." (PMID 22536524, 2012). "Using computer-aided image registration and analysis, the correlation of these markers with each other and with parameters derived from the abundance and location of CD34-positive tumor microvessels was analyzed." (PMID 22825389, 2012). "In our experience CD34 normally stains tumor vessels and host vessels undergoing neovascularisation as seen in liver regeneration (unpublished result) but stains mature vessels only minimally." (PMID 23153292, 2012). "Microscopically, the inner components of the tumor consisted of variously sized vascular spaces lined by a single layer of flattened cells, which stained positive with CD34 and vimentin." (PMID 23216883, 2012). "Immunohistochemical data also showed that the expressions of endothelial cell markers, CD31 and CD34 were markedly less in tumor sections of quercetin treated animals." (PMID 23094058, 2012). "According to the volume and immunohistochemistry of the tumors, the TSAVD-treated group showed a lower tumor volume and CD34 expression level (a lower blood vessel density)." (PMID 22956974, 2012). "The preliminary results of our study demonstrated that Cho/NAA is closely related to MIB-1, CD34 and tumour infiltration in HGG." (PMID 22729482, 2012). "CD34 is a marker of haematopoietic progenitor cells, stromal precursors, vascular endothelial cells, and a variety of stromal tumour cells." (PMID 22761655, 2012). "In HGG, higher Cho/NAA ratios were associated with a greater probability of higher MIB-1 counts, stronger CD34 expression, and tumour infiltration." (PMID 22729482, 2012). "The phenotype of tumor initiating cells, CD34+/CD38− cells, in leukemia is similar to normal hematopoietic progenitor cells." (PMID 23443123, 2012). "These tumor masses also exhibited microvascular proliferation characterized by a substantially increased number of CD34-positive microvessels." (PMID 22650359, 2012).
tumor (continued). "We observed that AdvGFP/MDA-7 down-regulated vessel expression of vascular endothelial growth factor (VEGF) and CD34, reduced vessel density in tumors, and inhibited tumor growth in a nude mouse tumor model." (PMID 23554730, 2012). "The mode of tumor growth, the low mitotic index, the polyclonality of lymphoid markers and the negativity of CD34 usually remove most of these diagnoses." (PMID 22805416, 2012). "The immunohistochemical study showed a diffuse and intense c-kit and CD34 expression, confirming the stromal tumour type, whereas the other differentiation markers were negative (desmin and actin)." (PMID 22826743, 2012). "Immunohistochemical data was also showed that the expressions of endothelial cell markers, CD31 and CD34 were markedly less in tumor sections of luteolin treated animals." (PMID 23300633, 2012). "12-O-tetradecanoylphorbol-13-acetate (TPA)-induced HF stem cell activation and tumor formation in mice requires CD34." (PMID 22383956, 2012). "In a few specimens, optimal thresholding of CD34-positive pixels also proved to be more difficult, since the tumor cells also showed a signal." (PMID 22825389, 2012). "The less aggressive tumor cells were positive for CD34 and smooth muscle actin (SMA), with a Ki-67 index of 2%, while the highly aggressive tumor cells were negative for CD34 and negative or weakly positive for SMA, with a Ki-67 index of 21%." (PMID 23227375, 2012). "In normal saline-treated mice, many CD34 positively stained vessels were diffusely located and formed tube-like structures in tumor." (PMID 22888341, 2012). "We examined the tumor tissues with anti-CD34 and the most highly vascularized area of each tumor was identified and five high-powered fields were counted in this area for MVD." (PMID 22529899, 2012). "We analyzed the expression of CD34 in intrahepatic and lung metastatic tumor nodules by IHC staining." (PMID 22384233, 2012). "Tumour CD8+ infiltrate was directly associated with CD68+ infiltration (P<0.01), CD34+ (P<0.05) and neo-adjuvant therapy (P<0.05)." (PMID 22240784, 2012). "In our experience CD34 only stains tumor vessels and vessels undergoing neoangiogenesis as seen in liver regeneration (unpublished data)." (PMID 23153292, 2012). "Analysis of carbocyanine/CD31 co-localization did reveal a slightly higher proportion of perfused vessels in Cd34−/− tumor tissues, compared to Cd34+/+, suggestive of a slight increase in the proportion of functional vessels." (PMID 21494591, 2011). "In this regard, across a broad range of tumor types, CD34 is expressed on tumor vasculature and on spindle cells in a variety of skin lesions." (PMID 21494591, 2011). "At later stages, subcutaneous tumor growth was accelerated in Cd34−/− mice and surpassed growth in wildtype mice." (PMID 21494591, 2011). "Ly5.1 mice reconstituted with Cd34−/− bone marrow exhibited increased tumor size on day 19, compared to mice reconstituted with Cd34+/+ bone marrow." (PMID 21494591, 2011). "In light of these findings, extra care should be taken when evaluating CD34 expression as the sole marker of tumor vasculature." (PMID 21494591, 2011). "Bone marrow chimera experiments demonstrated this difference was due to a hematopoietic function for CD34 and, correspondingly we found reduced intra-tumor mast cell numbers in Cd34−/− mice." (PMID 21494591, 2011). "Most areas of the tumor showed a "typical" thickened hepatocytic trabecular pattern in reticulin stain and diffuse positive sinusoidal CD34 pattern on immunostain." (PMID 21338527, 2011). "Surprisingly, tumor size in Cd34−/− animals approached or even surpassed tumor size in Cd34+/+ control animals, at the day 19 end-point." (PMID 21494591, 2011).
tumor (continued). "In Cd34−/− animals at all time-points, intra-tumoral mast cell numbers are reduced, and at a later time-point (day 19) tumor growth surpasses Cd34+/+ controls." (PMID 21494591, 2011). "Similar to the increase in apoptosis, the decrease in CD34 staining was greatest in the AT1RLOW tumours (P = 0.0267 for AT1RHI compared to P = 0.0179 for AT1RLOW tumours)." (PMID 21703011, 2011). "In this study, we focused on the function of the membrane protein CD34 in the tumor-extrinsic microenvironment." (PMID 21494591, 2011). "Immunohistochemically, the tumor cells were strongly positive for CD34, CD99, Bcl-2, and vimentin and negative for smooth muscle actin (SMA), CD31, cytokeratin, S-100, CD117, and epithelial membrane antigen (EMA)." (PMID 21443810, 2011). "A variety of hematopoietic cells, including eosinophils and mast cells, which both express CD34, infiltrate tumor sites and interact with tumor cells and the surrounding microenvironment." (PMID 21494591, 2011). "In particular, CD34 is a useful marker that allows differentiation of DFSP tumor cells from normal stroma cells." (PMID 21214920, 2011). "Based on the previous findings of impaired vessel integrity in Cd34−/− mice, we also assayed vascular integrity in tumor tissues by injecting mice with fluorescent carbocyanine dye prior to sacrifice." (PMID 21494591, 2011). "Despite the presence of CD34 on both the vasculature and tumor-infiltrating immune cells, our study is the first to address a role for CD34 in the tumor microenvironment and highlight a tumor cell-extrinsic function for CD34 in tumor development." (PMID 21494591, 2011). "Though observed in the tumour periphery, serial sections showed remarkably few CD34+ murine endothelial cells amongst the CD99+ tumor cells, Chalkley counts typically <2±0.4." (PMID 21779348, 2011). "In aggregate, our analysis reveals a novel role for CD34 in both early and late tumor growth and provides novel insights into the role of the tumor microenvironment in tumor progression." (PMID 21494591, 2011). "In cancer studies, CD34 is often used as a marker of tumor vasculature and CD34+ staining is used to characterize vascular patterns within tumor tissues." (PMID 21494591, 2011). "Merged images were used to quantify the proportion of total tumor cells that migrated into the lung parenchyma, revealing increased tumor cell extravasation in Cd34−/− lungs, compared to Cd34+/+ controls." (PMID 21494591, 2011). "Our results show that at an early time-point, tumor growth is decreased in Cd34−/− animals, in both primary tumors (at day 14) and lung metastases (day 12), and that this is associated with impaired vascular integrity." (PMID 21494591, 2011). "As hematopoietic CD34 is predominantly expressed on mast cells and eosinophils, we further examined the roles of these cells in regulating tumor growth." (PMID 21494591, 2011). "In immunohistochemical stains, a positive sinusoidal CD34 stain was diffusely present in areas of tumor, but only focally and weakly present in the area of cirrhosis." (PMID 21338527, 2011). "In a colorectal polyp model, we demonstrated the importance of CD34 expression on infiltrating mast cells, resulting in increased tumor angiogenesis in polyp formation." (PMID 21494591, 2011). "Our unpublished data from previous studies showed that ANGII infusion increased the length of CD34+ endothelium in tumours while irbesartan decreased CD34+ endothelium compared to tumours from control (untreated) animals." (PMID 21703011, 2011). "This study presents novel insights into CD34 function on vasculature and expands our understanding of a role for CD34 in hematopoietic cell migration during tumor development." (PMID 21494591, 2011). "Reduced numbers of lung metastases were also observed in Cd34−/− mice at day 12, despite increased initial tumor cell extravasation into the lung 4 hours after injection." (PMID 21494591, 2011).
tumor (continued). "In conclusion, our study demonstrates that CD34 promotes tumor growth at an early time-point (day 14), by playing a key role on vasculature, maintaining appropriate vessel integrity." (PMID 21494591, 2011). "Fourteen days after s.c. injection, tumor size was significantly smaller in Cd34−/− animals, compared to wildtype controls." (PMID 21494591, 2011). "Immunohistochemical approaches to differentiate between these entities included the expression of androgen receptor, CD34, bcl-2, TGF-[beta], CD10, and staining for tumor-associated Merkel cells." (PMID 21152127, 2011). "At the later time-point (day 19), we found that tumor size is increased in Cd34−/− mice, following CD34 ablation in hematopoietic cells." (PMID 21494591, 2011). "Within these lesions, CD34 expression has been used diagnostically and has been proposed as a prognostic indicator, as CD34 staining correlates with the extent of tumor angiogenesis." (PMID 21494591, 2011). "In the lone study examining a functional role for CD34 in tumor cells, Cd34−/− mice exhibited reduced tumor growth, compared to wildtype animals, following administration of 7,12-dimethylbenz(a)anthracene (DMBA) and 12-O-tetradecanoylphorbol-13-acetate (TPA)." (PMID 21494591, 2011). "CD34 expression in the tumor microenvironment has been extensively reported in human and mouse cancers." (PMID 21494591, 2011). "In one case, a dense cluster of CD34+ cells was found closely adjacent to the main tumour mass and this region colocalised with CD99+ human cells." (PMID 21779348, 2011). "Based on our findings, we predict that if CD34 expression is lost or reduced on tumor vasculature, there would be functional effects on vascular integrity and tumor growth." (PMID 21494591, 2011). "In summary, we observed increased vascular leakage and altered vessel structure in tumors from Cd34−/− mice, suggesting a role for CD34 in the maintenance of tumor vessel integrity, a limiting factor in tumor growth." (PMID 21494591, 2011). "CT images reveal an organized vascular network in tumors from Cd34+/+ mice, with large vessels of uniform diameter at the tumor periphery and an intricately branched microvascular network throughout the tumor interior." (PMID 21494591, 2011). "In the present case, the tumor cell accumulation is demonstrated to be confined within the peritubular capillary walls, by anti-CD34 staining." (PMID 21943175, 2011). "In the current study, we observed biphasic functional roles for CD34 in the tumor microenvironment during tumor progression." (PMID 21494591, 2011). "MVD values were assessed by staining these with CD34 in tumor tissues that were removed from SKOV-3 xenografts." (PMID 20723224, 2010). "The mean total length of CD34-positive vessels in WP1066-treated tumours was significantly (P<0.05) shorter than that in vehicle-treated control tumours." (PMID 20461084, 2010). "Immunohistochemical staining of the tumor tissue demonstrated strongly positive reactivity to CD 117 (c-kit) and CD34 in almost all the tumor cells." (PMID 21054898, 2010). "In the lung metastasis model, treatment with TGF-β pathway antagonists inhibited tumor angiogenesis, as reflected by a decrease in CD34-positive microvessel density." (PMID 20504320, 2010). "After 3 days of BMS-690514 administration (30 mg kg−1 day−1), the proportion of tumour vessels seemed to be lesser than that in vehicle-treated controls and a qualitative reduction in CD34-positive vessel area was observed." (PMID 20628392, 2010). "PADI4 is expressed in CD34+ stem cells in normal tissues, and many more CD34+ cells expressing PADI4 are present in tumour tissues." (PMID 20222985, 2010). "We selected CD31 to label endothelial-dependent vessel for the reasons: Because CD31/CD34 is a pan endothelial marker, and hence stains nearly all blood vessels, both stable vessels trapped inside the tumor and neoangiogenesis." (PMID 20525189, 2010).
tumor (continued). "After 3 days of BMS-690514 administration (30 mg kg−1 day−1), the proportion of abnormal tumour vessels seemed to be lesser than that in vehicle-treated controls and a qualitative reduction in CD34-positive vessel area was observed." (PMID 20628392, 2010). "Alternatively, ex vivo generated monocytic or CD34-derived DC loaded with tumor antigen can be utilized for specific active immunotherapy of cancer patients." (PMID 21253471, 2010). "On the other hand, the immunohistochemical profile of the tumour included intense positivity for CD34." (PMID 20525288, 2010). "Immunohistochemically, the stromal cells of the tumor show strong positivity for vimentin and variable positivity for desmin, α-smooth muscle actin, and CD34." (PMID 21143833, 2010). "Immunohistochemical staining of the tumor tissue demonstrated strongly positive reactivity to CD 117 (c-kit) and CD34 in almost all the tumor cells, whereas a small percentage of the neoplastic cells was positive for α-smoth muscle actin." (PMID 21054898, 2010). "Here we found a slight increase in the level of CD34 positive staining endothelium in the tumours of CGP42112A treated mice and a significant increase in VEGF secreted by CGP42112A treated MoCR cells in vitro." (PMID 20584290, 2010). "Immunohistochemical studies have shown moderate-to-strong staining of human progenitor cell antigen CD34 in tumor cells." (PMID 20525288, 2010). "Analysis of total CD34 positive cells revealed an increase in the number of small vessels and a significant decrease in the number of large vessels (p<0.001) in tumours treated with Fsn0503." (PMID 20824056, 2010). "Tumor specimens were paraffin-embedded and immunohistochemistry was performed with primary antibody against CD-34 to count MVD." (PMID 19323831, 2009). "Studies of CD34-positive hematopoietic stem cell incorporation into tumor neovasculature and of neural progenitor cell migration to sites of spinal cord injury showed that such labeled stem cells were visible by MRI up to 1–2 weeks after their administration." (PMID 19787043, 2009). "Treatment with VEGFR3-Ig had, however, less obvious effects on CD34-positive blood capillary density and tumor size than in parental PC-3 tumors." (PMID 19821979, 2009). "CD34-lineage- cells cultured with IL-15 and IL-21 for 4 weeks were assayed for NK activity against NK-sensitive tumour cell targets." (PMID 19712464, 2009). "These CD34+ iMCs promote tumour growth by expression of the matrix metalloproteinases, MMP9 and MMP2, and the CC-chemokine receptor 1 (CCR1), and migrate towards the CCR1 ligand CCL9, highly increased in the tumour epithelium." (PMID 18506144, 2008). "For example, in leukaemia, the ability to initiate new tumor growth resides in a rare phenotypically distinct subset of tumor cells that are defined by the expression of CD34+CD38- surface antigens and have been termed leukemic stem cells." (PMID 18492237, 2008). "Analysis of the CD34-stained tumour sections revealed that the size of the areas with vital tumour cells correlated with the density of vessels spreading from the subderma into the tumour nodule." (PMID 18447912, 2008). "In benign nodules, positive staining of CD34 manifested that a smaller quantity of staining tumor capillaries were observed." (PMID 18590539, 2008). "MVD is the number of microvessel per unit area which is counted by using some specific antibodies (for instance CD34 monoclonal antibody)to mark microvessel endothelial cells of tumor tissues." (PMID 18590539, 2008). "Down-regulated genes in E2-treated CD133+/CD34+ cells also included the newly characterized tumor suppressor genes DOCK4, a member of the CDM gene family, and SPARCL1, which encodes an extracellular matrix-associated glycoprotein." (PMID 17559657, 2007).